MDM4 (MDM4 regulator of p53)
Diseases named in the same sentence as MDM4 in open-access papers (continued):
Sharing a sentence is not in itself a finding about the gene and the disease.
retinoblastoma (continued). "Initially developed for Parkinson’s disease, CEP-1347 is a pharmacological inhibitor of MDMX that has also been shown to suppress the expression of MDM4 in retinoblastoma cell lines." (PMID 37509256, 2023). "In our collection of retinoblastomas, MDM4 and OTX2 copy number gains were found in 16 (42%) and five (13%) of 38 retinoblastoma, respectively." (PMID 28211617, 2017). "Other copy number changes reported in retinoblastoma include gains of DDX1, MDM4 and OTX2, and loss of BCOR and RBL2." (PMID 29124525, 2017). "MDM4 was found to be up-regulated in invasive breast carcinoma (by 14.2%), liver hepatocellular carcinoma (by 12.4%), retinoblastomas (by 65%), skin cutaneous melanomas (by 12%), and stage II–V melanomas (by > 65%)." (PMID 27738340, 2016). "For example, MDM4 is found on a region of chromosome 1 that is gained in 45% of retinoblastomas but the gene and protein are increased in virtually all retinoblastomas." (PMID 24509483, 2014). "MDMX mice (Chx10-Cre;RbLox/Lox;p107−/−;MDMXTg) have conditional overexpression of the MDMX gene to mimic the elevated expression of MDMX (Mdm4) in human retinoblastomas." (PMID 23765217, 2013). "Within the recurrent focal gains or losses in the RbTKO retinoblastoma model, we found 12 in cancer genes, including Lmo1 in 5/6 samples; Ndrg1, Brd4, Fbxo11, and Rbm15 in 4/6 samples; Mdm4, Msi2, and Ezh2 in 3/6 samples." (PMID 23765217, 2013). "The frequency of MDM4 overexpression varies by cancer type; for example, a majority of retinoblastomas show amplification of MDM4, but it is very uncommon in prostate cancer." (PMID 22870278, 2012). "We also discovered that MDM4 protein steady state levels are much higher in retinoblastoma than in human fetal retinae." (PMID 22916154, 2012). "To test if there was any correlation between the SNP genotypes and MDM2 and MDM4 gene expression in retinoblastoma, we performed gene expression arrays on 22 of the 44 primary retinoblastoma tumors using the U133av_2 affymetrix chip." (PMID 22916154, 2012). "We recently performed gene expression array analysis of 52 human retinoblastomas and discovered that MDM4 was expressed at high levels in all 52 tumors irrespective of the MDM4 copy number." (PMID 22916154, 2012). "We also explored the role of miR-191 in regulating MDM4 mRNA and protein expression in retinoblastoma." (PMID 22916154, 2012). "Immunoblotting confirmed that MDM4 protein was expressed at high levels (∼5–65 fold increase) in our retinoblastoma orthotopic xenografts relative to fetal retina and U2OS cells." (PMID 22916154, 2012). "Additional samples with the C/A or C/C genotype would be required to provide statistically significant data on the relationship between miR-191 levels and MDM4 mRNA in retinoblastoma." (PMID 22916154, 2012). "We also discovered that a microRNA predicted to target MDM4 (miR191) was downregulated in retinoblastoma relative to human fetal retinae and a subset of samples had somatic mutations that eliminated the miR-191 binding site in the MDM4 mRNA." (PMID 22916154, 2012). "We propose that the increased MDM4 protein expression in retinoblastoma is regulated by post-transcriptional mechanisms." (PMID 22916154, 2012).
retinoblastoma (continued). "In this study, we analyzed the MDM2 and MDM4 mRNA and protein expression in human fetal retinae and human retinoblastoma." (PMID 22916154, 2012). "We identified and validated two alternatively spliced forms of MDM4 in retinoblastoma orthotopic xenografts that have been previously reported." (PMID 22916154, 2012). "MDM4 is overexpressed in about 17% of all cancers and more frequently in some types, such as colon cancer or retinoblastoma." (PMID 22870278, 2012). "We also characterized the expression of miR-191 in retinoblastoma as compared to human fetal retinae and sequenced MDM4 SNP34091 where miR-191 binds." (PMID 22916154, 2012). "Taken together, we propose that MDM4 protein levels are increased in retinoblastoma through multiple post-transcriptional mechanisms." (PMID 22916154, 2012). "The importance of MDM4 in human cancer is underscored by its frequent amplification in certain tumor types, such as colon cancer, gliomas and retinoblastomas." (PMID 22870278, 2012). "While the affinity of the MDM2 antibody used in this study was much lower than the MDM4 antibody, there was still significantly more MDM4 protein in retinoblastoma xenografts than MDM2 (>50 fold)." (PMID 22916154, 2012). "We demonstrated that the MDM4 mRNA is alternatively spliced in primary human retinoblastomas in a pattern that is predicted to produce altered versions of the MDM4 protein that have been shown to be oncogenic and more stable than the full-length protein." (PMID 22916154, 2012). "Amplification of the MDM4 gene has also been reported in several tumour types, with MDM4 amplification observed in 65% of retinoblastomas." (PMID 21197471, 2011). "Unlike gliomas, which exhibit high-level focal amplifications of MDM4 examination of a large panel of retinoblastomas with 1q gain revealed low-level MDM4 gain in retinoblastoma." (PMID 18489754, 2008). "New classes of small molecule MDM2/MDM4 inhibitors are being evaluated in Phase I/II studies in combination with broad-spectrum and targeted therapies; one of these is a trial in pediatric cancer including retinoblastoma." (PMID 35433448, 2022). "Importantly, the level of MDM4 protein was elevated in retinoblastoma as compared to human fetal retina, but the mRNA levels were similar as measured with gene expression arrays and real time RT-PCR." (PMID 22916154, 2012). "For example, MDM2 expression may be important for the initiation of retinoblastoma but it may be subsequently downregulated with concomitant upregulation of MDM4." (PMID 22916154, 2012). "Taken together, these data suggest that post-transcriptional mechanisms may contribute to stabilization of the MDM4 protein in retinoblastoma." (PMID 22916154, 2012).
retinoblastoma (continued). "However, MDM4 amplification is often viewed as the markers of malignancy such as retinoblastomas." (PMID 38281029, 2024). "Therefore, targeting Mdm4 in human and mouse retinoblastoma may be relevant with respect to preclinical testing." (PMID 23765217, 2013). "While the comparison of MDM2 and MDM4 protein levels across cell lines clearly shows that the relative abundance of the proteins is different, it is impossible to directly compare the absolute levels of MDM2 and MDM4 in retinoblastoma samples because the antibodies may have different affinities." (PMID 22916154, 2012). "Sporadic retinoblastoma has not been analyzed for MDM2 or MDM4 polymorphisms." (PMID 22916154, 2012). "In our previous study on the effects of CEP-1347 on retinoblastoma cells, we showed that the CEP-1347-mediated inhibition of MDM4 expression increased the expression of MDM2 in one cell line but decreased that of MDM2 in another." (PMID 37686602, 2023). "Of these, only the dual MDM2/MDM4 inhibitor, ALRN-6924 in combination with cytarabine is under investigation in retinoblastoma." (PMID 36338723, 2022). "Here we quantify the expression of MDM4 and MDM2 mRNA and protein in human fetal retinae, primary retinoblastomas, retinoblastoma cell lines and several independent orthotopic retinoblastoma xenografts." (PMID 22916154, 2012). "In a series of orthotopic xenografts of human retinoblastoma from our lab and Memorial Sloan Kettering Cancer Center (MSKCC), MDM4 protein was expressed at high levels and MDM2 was below the limit of detection." (PMID 22916154, 2012). "Here, we genotyped MDM4 SNP7, MDM4 SNP34091, and MDM2 SNP 309 in 44 retinoblastoma tumors, their corresponding blood DNA, and 3 human orthotopic xenografts." (PMID 22916154, 2012). "Analyzing recently published data on genomic alterations related to annotated genes for a 102-cohort, reveals that loss of chr16q22.2 (containing DHODH) is amongst the most frequent alterations in retinoblastoma and comparable to MYCN and MDM4 gain/amplification." (PMID 38332874, 2024). "Nonetheless, MDM2 and MDM4 are both expressed in all Rb cone clusters, likely impeding an ARF-mediated response and further promoting cone proliferation and survival in Rb tumors." (PMID 34003213, 2021). "Importantly, there were also copy number gains in MDM4 and MYCN which are common in retinoblastomas." (PMID 34315877, 2021).
retinoblastoma (continued). "In spite of its significantly lower affinity toward MDM4 than toward MDM2, the near absence of MDM2 in a retinoblastoma model with elevated MDM4, resulted in remarkable response when the drug was administered directly to the tumor site." (PMID 30689920, 2019). "Opposed to glioma where minimal regions of 1q gain exclusively included MDM4, target gene identification of 1q gain in retinoblastoma is not conclusive yet." (PMID 27126562, 2016). "The distribution of the MDM4 SNP34091 in our retinoblastoma cohort was not significantly different from that of the general population but we did identify somatic mutations C/A->A/A at SNP34091 in two patients." (PMID 22916154, 2012). "Specifically, MDM4 SNP7 T/T and/or SNP34901 A/A may contribute to tumor progression in retinoblastoma patients." (PMID 22916154, 2012). "Importantly, the addition of Nutlin, an MDM4/MDM2 antagonist led to death of retinoblastoma cell lines and synergized with traditional chemotherapy in an orthotopic retinoblastoma mouse model." (PMID 18489754, 2008).
glioblastoma (30 papers, 2012 to 2025). The most malignant astrocytic tumor (WHO grade IV). "We observed MDM4 amplification, which has been reported to be associated to the chromotripsis phenomenon in glioblastoma progression." (PMID 29844869, 2018). "A total of 24 single-nucleotide polymorphisms (SNPs) of the MDM4 gene were assessed in a dataset of 562 glioma patients (non-glioblastoma) and 1,192 cancer-free controls." (PMID 30038284, 2018). "Gain at 1q32.1, the chromosomal region encoding for PIK3C2B and MDM4 has been reported in studies assessing copy-number alterations in glioblastoma multiforme." (PMID 29088297, 2017). "By contrast, other genes including CDK4 and MDM4 frequently amplified in glioblastoma were also amplified in human neural progenitor cells during differentiation." (PMID 28415661, 2017). "No tumors demonstrated EGFR amplification, MET amplification, CDK4 amplification, MDM2 or MDM4 amplification, PTEN homozygous deletion, or NF1 homozygous deletion that are frequent oncogenic events in conventional IDH-wildtype glioblastomas." (PMID 38079020, 2023). "Genes known to be the most frequently amplified in glioblastoma, EGFR, CDK4, PDGFRA, MDM2, MDM4 are all found to be involved in tumorigenesis of a variety of cancers and are members of several signaling pathways notoriously involved in cancer." (PMID 30871102, 2019). "Some known oncogenes and tumour suppressors are only captured by RUBIC, such as MDM4 in breast, APC in colon and EGFR in Glioblastoma." (PMID 27396759, 2016). "Those genes include EGFR, PDGFRA, FGFR3, PIK3CA, MDM4, CDKN2A/B, PTEN and are all members of the core alterated pathways in glioblastoma controlling key phenotypes such as proliferation, apoptosis and angiogenesis." (PMID 25679508, 2015).